RN7SL259P (RNA, 7SL, cytoplasmic 259, pseudogene)
Gene: Miscellaneous RNA gene on chromosome 11 (62,935,982 to 62,936,234, reverse strand). Ensembl gene ENSG00000241082.
Homologues: Orthologues: chimpanzee Metazoa_SRP (99% identical), macaque Metazoa_SRP (92% identical). Paralogues in human: RN7SL45P (82% identical), RN7SL1 (81% identical), RN7SL2 (81% identical), RN7SL186P (80% identical), RN7SL386P (80% identical), RN7SL126P (80% identical), RN7SL3 (80% identical), RN7SL608P (80% identical), RN7SL566P (79% identical), RN7SL597P (79% identical), RN7SL709P (79% identical), RN7SL799P (79% identical), and 706 more.